RRS1 (regulator of ribosome synthesis 1)
Description:
Involved in ribosomal large subunit assembly. May regulate the localization of the 5S RNP/5S ribonucleoprotein particle to the nucleolus.
Synonyms: KIAA0112
Tractability: Small molecule: a structure with a bound ligand is known. PROTAC: UniProt records ubiquitination sites on it; ubiquitination databases record sites on it; its protein half-life has been measured.
Gene: Protein-coding gene on chromosome 8 (66,429,014 to 66,430,733, forward strand). Ensembl gene ENSG00000179041.
Subcellular location: Nucleus, nucleolus
Subcellular location (Human Protein Atlas): Nucleoli
Gene Ontology:
Molecular function: 5S rRNA binding; protein binding; RNA binding
Biological process: mitotic metaphase chromosome alignment; protein localization to nucleolus; ribosomal large subunit assembly; ribosomal large subunit biogenesis; endonucleolytic cleavage in ITS1 to separate SSU-rRNA from 5.8S rRNA and LSU-rRNA from tricistronic rRNA transcript (SSU-rRNA, 5.8S rRNA, LSU-rRNA); ribosome biogenesis
Cellular component: condensed nuclear chromosome; nucleolus; preribosome, large subunit precursor; endoplasmic reticulum; nucleus
Genetic constraint (gnomAD): Loss-of-function variants: 11 observed, 25.52 expected, observed/expected ratio (o/e) 0.43, 90% interval 0.27 to 0.71. The upper end of that interval is the gene's LOEUF score, 0.71, which puts it in group 2 of 6, group 1 being the genes least tolerant of losing a copy. Missense variants: 485 observed, 503.62 expected, observed/expected ratio (o/e) 0.96, 90% interval 0.89 to 1.04. Synonymous variants: 198 observed, 213.36 expected, observed/expected ratio (o/e) 0.93, 90% interval 0.83 to 1.04.
Homologues: Orthologues: chimpanzee RRS1 (99% identical), macaque RRS1 (98% identical), pig RRS1 (95% identical), dog RRS1 (94% identical), rat Rrs1 (92% identical), mouse Rrs1 (91% identical), guinea pig RRS1 (90% identical), rabbit RRS1 (86% identical), zebrafish rrs1 (61% identical), Drosophila melanogaster CG32409 (41% identical), Caenorhabditis elegans rrsr-1 (37% identical), tropical clawed frog rrs1 (23% identical).
Diseases named in the same sentence as RRS1 in open-access papers:
RRS1 is named in the same sentence as 31 diseases in open-access papers, as found by Europe PMC text mining. Sharing a sentence is not in itself a finding about the gene and the disease. The quoted sentences say what the papers report.
breast carcinoma (12 papers, 2018 to 2024). "Clinical metadata showed that TNBC/basal-like breast cancers express elevated levels of ribosome biogenesis regulators and high RRS1 levels are associated with poor prognosis." (PMID 32054925, 2020). "High RRS1 expression levels were associated with poor breast cancer prognosis, and RRS1 knockdown inhibited breast cancer proliferation in vitro and in vivo." (PMID 30320499, 2018). "Here, we report that RRS1 is associated with cisplatin resistance in breast cancer cells." (PMID 37049702, 2023). "Therefore, RRS1 knockdown in breast cancer cells induced apoptosis and caused detectable alterations in the cell cycle distribution." (PMID 30320499, 2018). "In addition, we analysed the association between the clinicopathological variables and RRS1 expression in 242 breast cancer samples." (PMID 30320499, 2018). "This suggests that RRS1 plays an indispensable role in the occurrence and development of breast cancer." (PMID 38474562, 2024). "Cisplatin treatment upregulated RRS1 in breast cancer cells, and the subsequent knockdown of RRS1 reversed the drug resistance of MCF-7/DDP cells." (PMID 37049702, 2023). "We confirmed that RRS1 promotes the proliferation of breast cancer cells and inhibits apoptosis, whereas apoptosis inhibition was one of the mechanisms of cisplatin resistance." (PMID 37049702, 2023). "To further detect the role of RRS1 in breast cancer cells’ cisplatin resistance, we silenced the RRS1 gene using specific shRNA, which significantly decreased both mRNA and protein expression." (PMID 37049702, 2023). "Our study is the first to show that RRS1 sensitizes breast cancer cells to cisplatin by binding to AEG-1, and it provides a theoretical basis to improve the efficacy of cisplatin-based chemotherapy." (PMID 37049702, 2023). "Given that apoptosis resistance is one of the causes of the cisplatin resistance of tumor cells, our aim was to determine the relationship between RRS1 and cisplatin resistance in breast cancer cells." (PMID 37049702, 2023). "RRS1 (human regulator of ribosome synthesis 1), a critical nuclear protein involved in ribosome biogenesis, also plays a key role in the genesis and development of breast cancer by protecting cancer cells from apoptosis." (PMID 37049702, 2023). "The expression of RRS1 increased significantly in MCF-7 cells after 12 h of cisplatin treatment, suggesting that cisplatin can induce RRS1 expression in breast cancer cells." (PMID 37049702, 2023). "Recent studies show that RRS1 is aberrantly expressed in breast cancer, colorectal cancer, hepatocellular carcinoma and thyroid cancer and that is correlated to the proliferation and apoptosis of cancer cells." (PMID 37049702, 2023). "We found that the RRS1 gene is highly expressed in breast cancer cells, and its knockdown significantly reduced the proliferation rate and increased apoptosis." (PMID 33718361, 2021). "RRS1, a nuclear protein involved in ribosome biogenesis, has been reported to regulate cancer progression in hepatocellular carcinomas (HCCs) and breast cancer." (PMID 33224957, 2020). "In breast cancer, both the copy number and the mRNA expression of RRS1 increased in cancer tissues compared with normal tissues, and RRS1 overexpression was significantly correlated with lymph node metastasis and poor survival." (PMID 33224957, 2020). "Experimentally, RRS1 knockdown in breast cancer cells significantly reduced cell proliferation and tumour development in a mouse xenograft model." (PMID 30320499, 2018). "When breast cancer patients were stratified by their RRS1 expression, the patients with high RRS1 expression levels exhibited lower DFS than patients with low levels of RRS1 (P < 0.05)." (PMID 30320499, 2018).
breast carcinoma (continued). "RRS1 mRNA and protein levels were also significantly increased in a panel of human breast cancer cell lines." (PMID 30320499, 2018). "We observed that the expression levels of RRS1 were higher in human breast cancer tissues than in paired non‐cancerous tissues, and high RRS1 expression levels were associated with lymph node metastasis and poor clinical outcome." (PMID 30320499, 2018). "Immunohistochemistry (IHC) and RT‐qPCR analyses indicated that RRS1 was commonly overexpressed in breast cancer tissues." (PMID 30320499, 2018). "Our results demonstrated that RRS1 levels were significantly higher in breast cancer samples than in paired non‐cancerous (normal) tissues (P < 0.0001)." (PMID 30320499, 2018). "By analysing breast tissues, we observed that RRS1 mRNA was expressed at higher levels in breast cancer tissues than in paired non‐cancerous tissues." (PMID 30320499, 2018). "We further studied whether RRS1 could increase AEG-1 content in breast cancer drug-resistant cells by regulating protein stability." (PMID 37049702, 2023). "In conclusion, we show for the first time that RRS1 might regulate cisplatin resistance in breast cancer cells by inhibiting AEG-1 ubiquitination and proteasome degradation." (PMID 37049702, 2023). "We only got some preliminary results on the role of RRS1 in breast cancer cisplatin resistance." (PMID 37049702, 2023). "Furthermore, RRS1 also induces apoptosis resistance in breast cancer cells through the ERK/Bcl-2/BAX signaling pathway." (PMID 37049702, 2023). "Because apoptosis inhibition is one of the causes of cisplatin resistance, exploring the relationship between RRS1 and cisplatin resistance in breast cancer cells may determine the potential of ribosomal proteins as therapeutic targets." (PMID 37049702, 2023). "Also, the downregulation of lncRNA SET-binding factor 2-antisense RNA1 can upregulate miR-143 and inhibit RRS1 and ultimately restrict the progression of breast cancer." (PMID 37090698, 2023). "Taken together, RRS1 is a novel oncogene of breast cancer and a promising therapeutic target." (PMID 33718361, 2021). "RRS1 (human regulator of ribosome synthesis 1), an essential nuclear protein involved in ribosome biogenesis, is overexpressed in some human cancers, yet its role in breast cancer remains unclear." (PMID 30320499, 2018). "We have demonstrated here that RRS1 plays a functional role in breast cancer cell proliferation." (PMID 30320499, 2018). "In addition, this finding was supported by the observation that RRS1 mRNA levels were also higher in a panel of human breast cancer cell lines than in normal human mammary epithelial cells (HMECs) (P < 0.01)." (PMID 30320499, 2018). "RRS1 may be characterized as a biomarker and could provide a new possible target for breast cancer treatment." (PMID 30320499, 2018). "Moreover, an in vitro analysis indicated that RRS1 mRNA and protein levels were significantly increased in a panel of human breast cancer cell lines." (PMID 30320499, 2018). "RRS1 protein levels were increased in all three human breast cancer cell lines (P < 0.01)." (PMID 30320499, 2018). "Because RRS1 is highly overexpressed in breast cancer tissues, we investigated whether RRS1 depletion in human breast cancer cells would alter their proliferation ability." (PMID 30320499, 2018). "Here, we report a functional analysis of RRS1 in breast cancer and its likely mechanism." (PMID 30320499, 2018). "Here, we set out to assess the functional role of RRS1 in breast cancer." (PMID 30320499, 2018). "Knocking down RRS1 inhibited breast cancer proliferation in vitro and in vivo." (PMID 30320499, 2018). "While these three cell lines overexpress RRS1, they represent distinct subgroups of breast cancer." (PMID 30320499, 2018).
breast carcinoma (continued). "Regulator of ribosome synthesis 1 (RRS1), a crucial regulatory factor in ribosome biogenesis, exerts a remarkable impact on the progression of breast cancer (BC)." (PMID 38474562, 2024). "Therefore, we explored the effect of RRS1 on cisplatin resistance in breast cancer cells." (PMID 37049702, 2023). "Furthermore, RRS1 may augment breast cancer cell invasion and metastasis via the RPL11-c-Myc-SNAIL axis." (PMID 37090698, 2023). "Furthermore, the oncogenic role of RRS1 has also been identified in breast cancer." (PMID 33204686, 2020). "However, it is important to understand how RRS1 regulates cell proliferation in breast cancer." (PMID 30320499, 2018). "In conclusion, this newly discovered RRS1/GRP78 signaling axis provides a molecular and theoretical basis for further exploring the mechanisms of breast cancer invasion and metastasis." (PMID 38474562, 2024). "To this end, we evaluated RRS1 expression levels in a cisplatin-resistant (MCF-7/DDP) and its parental cisplatin-sensitive (MCF-7) breast cancer cell line." (PMID 37049702, 2023). "It has been shown that RRS1 is highly expressed in HCC, breast cancer, papillary thyroid carcinoma, and CRC." (PMID 33204686, 2020). "Therefore, RRS1 may be a promising target for breast cancer therapy." (PMID 30320499, 2018). "RRS1 overexpression occurred in 60.7% of the tumours and significantly correlated with DFS in breast cancer patients." (PMID 30320499, 2018). "Taken together, RRS1 increased AEG-1 protein levels in breast cancer cells without affecting their transcriptional activity." (PMID 37049702, 2023). "The aim of this study was to determine whether RRS1 and AEG-1 interact to mediate cisplatin resistance in breast cancer cells." (PMID 37049702, 2023).
cervical cancer (6 papers, 2020 to 2023). A primary or metastatic malignant neoplasm involving the cervix. "RRS1 is known to be upregulated in cervical cancer tissue, inhibits apoptosis, and promotes cancer cell proliferation, metastasis and invasion." (PMID 37654657, 2023). "What’s more, the similar function of RRS1 knockdown in cervical cancer cells has also been uncovered." (PMID 31952549, 2020). "In addition, RRS1 overexpression is related to the tumorigenesis and progression of several tumor types, such as gastric cancer, hepatocellular carcinoma, and cervical cancer 47-49." (PMID 33854615, 2021). "Therefore, RRS1 promotes cervical cancer development and progression." (PMID 33718361, 2021).
Autoimmunity (5 papers, 2013 to 2021). The occurrence of an immune reaction against the organism's own cells or tissues. "Tight genetic linkage of paired NLRs, such as Pik-1/Pik-2, RGA5/RGA4, RRS1/RPS4, or RPP2A/RPP2B, is thought to facilitate coregulation and coevolution, thereby ensuring proper cooperation between these NLRs and reducing the genetic load caused by autoimmunity." (PMID 34288868, 2021). "Notably, EDS1-dependent induced and repressed genes in the EDS1-YFPNLS #A5 transcriptome overlapped substantially with EDS1-dependent induced and repressed gene sets in RRS1/RPS4-mediated ETI or 35S:RPS4-HS autoimmunity." (PMID 27082651, 2016). "Thus, we propose that a balanced protein expression of RRS1 and RPS4 is required for both suppressing autoimmunity and functional recognition of the corresponding effectors." (PMID 32050020, 2020). "We found that RPS4 protein does not self-associate in the absence of RRS1, and that the previously reported RPS4 autoimmunity in tobacco and Arabidopsis is suppressed when co-expressed with RRS1." (PMID 28475615, 2017). "As in N. benthamiana and tomato, introduction of the RPS4/RRS1 pair did not induce autoimmunity, indicating that RPS4 and RRS1 are tightly regulated in cucumber." (PMID 23437080, 2013). "We used two of the promoters to express RRS1 and RPS4, and we avoided autoimmunity induced by excessive expression of RPS4 or non-recognition of PopP2 caused by excessive expression of RRS1-R." (PMID 32050020, 2020).
Huntington disease (5 papers, 2018 to 2024). Huntington disease (HD) is a rare neurodegenerative disorder of the central nervous system characterized by unwanted choreatic movements, behavioral and psychiatric disturbances and dementia. "The aberrant expression of RRS1 is associated with Huntington’s disease and cancer development." (PMID 33718361, 2021). "The association between RRS1 and diseases was first established in Huntington’s disease, wherein RRS1 significantly contributes to pathogenesis by promoting ER stress." (PMID 38474562, 2024). "The role of RRS1 had been found only in Huntington disease by induction of endoplasmic reticulum (ER) stress in neurons for cellular dysfunctions." (PMID 29449788, 2018). "According to the prediction by SIFT (predicted score: 0.01), this variant demonstrates the highest level of deleteriousness, and previous research has established that the Rrs1 gene serves as a potential molecular biomarker for mouse model of Huntington disease." (PMID 37889051, 2024). "Although there is evidence of direct interaction between RRS1 and AEG-1 in the endoplasmic reticulum to regulate the development of Huntington’s disease, it is unclear whether the interaction between these two proteins is involved in cisplatin resistance as well." (PMID 37049702, 2023).
colorectal cancer (4 papers, 2017 to 2021). A primary or metastatic malignant neoplasm that affects the colon or rectum. "A previous study has shown that RRS1 expression in colorectal cancer is higher than in the tumor-adjacent normal tissues." (PMID 33854615, 2021). "Downregulation of RRS1 induces G2/M cell cycle arrest, apoptosis, and angiogenesis, thereby inhibiting the proliferation of colorectal cancer cells." (PMID 33854615, 2021). "RRS1 is highly expressed in colorectal cancer (CRC) tissues, and its expression is inversely correlated with the survival of CRC patients." (PMID 33204686, 2020). "A study found that knockdown of ribosome biogenesis regulatory protein homolog (RRS1) also trapped colorectal cancer cells in the G2/M phase and finally resulted in their apoptosis." (PMID 32266933, 2020). "Previous studies reported that RRS1 knockdown induced cell cycle arrest at the G2/M phase and apoptosis in colorectal cancer cells." (PMID 33204686, 2020). "Despite extensive studies into its fundamental, the role of RRS1 in colorectal cancer remains largely unclear." (PMID 29137316, 2017).
hepatocellular carcinoma (4 papers, 2018 to 2023). A malignant tumor that arises from hepatocytes. "In addition, it was also found that the expression level of the RRS1 gene in hepatocellular carcinoma tissue was significantly higher than that in adjacent tissue, and the RRS1 gene was related to the proliferation, apoptosis, invasion and metastasis of liver cancer SMMC-7721 cells." (PMID 37654657, 2023).
liver cancer (4 papers, 2020 to 2023). An epithelial or non-epithelial malignant neoplasm that arises from the liver. "Interfering with the expression of RRS1 can promote the apoptosis of liver cancer cells and inhibit the proliferation of liver cancer cells." (PMID 34712323, 2021). "RRS1 is overexpressed in liver cancer tissues relative to the para-carcinoma tissues, and the overall and disease-free survival rates of patients with high RRS1 expression are significantly lower than that in RRS1low patients." (PMID 33718361, 2021). "Therefore, RRS1 functions as a pro-tumorigenic factor in liver cancer." (PMID 33718361, 2021).
colon cancer (3 papers, 2017 to 2023). "Recent studies have also shown that RRS1 is overexpressed in liver and colon cancers and is associated with tumor proliferation." (PMID 37654657, 2023). "Next, we analyzed RRS1 expression in 334 colon tumor tissue and 28 normal tissue using RNA sequencing." (PMID 29137316, 2017). "The results showed that RRS1 was significantly over-expressed in the colon tumor tissues." (PMID 29137316, 2017). "Taken together, our findings provide evidence that RRS1 may promote the development of colon cancer." (PMID 29137316, 2017).
lymph node metastasis (3 papers, 2018 to 2022). "In addition, elevated RRS1 expression levels were correlated with lymph node metastasis and unfavorable clinical outcome." (PMID 35027621, 2022). "In addition, RRS1 overexpression was significantly correlated with lymph node metastasis and poor survival." (PMID 30320499, 2018).
papillary thyroid carcinoma (3 papers, 2018 to 2023). "Thus, enlarge the sample size is necessary to evaluate the diagnostic value of RRS1 for papillary thyroid carcinoma both in children and adults." (PMID 29449788, 2018). "In addition, dysregulation of RRS1 is involved in the development of several malignancies and the progression of various tumors, including papillary thyroid carcinoma, retinoblastoma, and neuroblastoma." (PMID 37090698, 2023). "In conclusion, these data afford a comprehensive view of a novel function of human RRS1 by promoting cell proliferation and could be a potential indicator for papillary thyroid carcinoma." (PMID 29449788, 2018).